CD4 (CD4 molecule)
Diseases named in the same sentence as CD4 in open-access papers (continued):
Sharing a sentence is not in itself a finding about the gene and the disease.
infection (continued). "CO also predicted lower age-adjusted counts of B cells and naïve CD4+ T cells and a lower CD4/CD8 T cell ratio, an immune profile that has been associated with vulnerability to infection in other populations." (PMID 40668911, 2025). "Decreased frequencies of naïve CD4 and CD8 T cells (p=0.016 and p=0.038, respectively) and increased frequency of CD4 CM and EM TIGIT+ T cells (p=0.022) were associated with development of infection." (PMID 40475763, 2025). "Primary CD4+ T cells isolated from PBMC from three individual healthy donors were infected with HIV-1 at a multiplicity of infection (MOI) of 1 for 96 h." (PMID 41085277, 2025). "CD8+ T cell and CD4+ T cell responses following natural infection have been reported to be stable for over 8 months." (PMID 40872762, 2025). "DCs can transfer HIV to CD4 T cells via two distinct mechanisms: first-phase transfer, also referred to as trans-infection, and second-phase transfer, or cis-infection." (PMID 39861894, 2025). "Subsequent infection with HIV-1 revealed that primary CD4+ T cells nucleofected with crPLIN3-3 produced significantly lower levels of HIV-1 p24 (P = 0.0008) in the supernatants compared with control cells." (PMID 41085277, 2025). "Among cases diagnosed in 2023 with available information on CD4 cell count, 24.0% were identified as recent infections, implying that these individuals acquired the infection within 12 months of diagnosis." (PMID 41011735, 2025). "In summary, we conclude from this study that Eng2 homologs were expressed on the infectious or tissue form of these dimorphic fungi during natural infection and elicited functional memory CD4+ T cells with clinical significance." (PMID 41061037, 2025). "In the present study, we have further investigated the influence of the purinergic system on the CD4+ T cells with potential cytotoxic capacity in the context of murine in vitro activation and in vivo infection with T. cruzi." (PMID 40590226, 2025). "We show that despite poor recognition of KSHV-infected B cells by LANA-specific TCR-transduced T cells in vitro, CD4+ LANA-specific effector memory T cells (TEM) accumulate at infection sites in vivo and acquire an early differentiated TEM phenotype." (PMID 41350288, 2025). "The CD4+ T response was dominant towards capsid, and overall, T cell epitopes extensively overlapped with epitopes detected after natural infection." (PMID 40820807, 2025). "To test this, we depleted CD4 T cells in primary and CoMtb-infected mice using anti-CD4 antibody, with the depletion beginning 1 day prior to infection, and examined lesion structures and lung CFU 35 days later." (PMID 40736456, 2025). "In the third phase, MDV is reactivated from CD4+ T cells in response to intracellular or extracellular stimuli, which is accompanied by a second cytolytic infection and immunosuppression at approximately 18 dpi." (PMID 39840986, 2025). "This was corroborated by assessment of polyclonal CD11ahi CXCR3+ CD4+ T cells at 7-days post-infection (Fig 1Bi-ii)." (PMID 40132035, 2025). "A similar trend was also observed in the rRB-1B_Meq-infected group, suggesting cytolytic infection in CD4+ T cells in both rMDV-infected groups." (PMID 40733525, 2025). "The following day, T cells were isolated from the spleens of mice infected with IAV (X31; day 9/10 post-infection) to generate a pool of IAV-specific CD4 and CD8 T cells." (PMID 40750594, 2025). "However, this case suggests that L. (L.) amazonensis infection may inhibit the activation of genetic pathways essential for DTH expression, most likely linked to the CD4+/Th1-type immune response, thereby compromising macrophage-mediated resistance to infection." (PMID 40764931, 2025). "Together, these results suggest that macrophages contribute, at least in part, to CD4+ T cell activation during infection." (PMID 40746561, 2025).
infection (continued). "Our experimental data demonstrate that the immune system is compromised as early as 7 days after infection, with a rapid rise of SIV copies in ml and a significant drop of CD4/CD8 ratio below ~1 within the first 14 days of infection." (PMID 40093003, 2025). "Upon examining the LCMV-specific CD4+ T cells at day 3 post s.c. infection, we noted an increase in the Tcf-1+ population coupled with a decrease in GzmB+ cells when IFN-γ was blocked." (PMID 40169810, 2025). "Surprisingly, studies in AGM and SM have shown that preservation of gut functionality occurs despite acute depletion of CD4+ T cells in the gut already in the first month of infection, in contrast with relatively stable CD4+ T cell counts in peripheral blood." (PMID 39842407, 2025). "The complex immune response induced by natural infection likely results from prolonged antigen exposure, driving robust activation of CD4 and CD8 T cells, natural killer (NK) cells, memory B cells, and nAbs52." (PMID 40328892, 2025). "It plays a well-documented role in enhancing HIV-1 transmission by binding to the viral envelope glycoprotein gp120, facilitating viral capture, and promoting trans-infection of CD4+ T cells." (PMID 40901106, 2025). "Specifically, the infection of CD4+ T-cells leads to their depletion, which critically weakens the immune system’s ability to combat the virus and increases susceptibility to opportunistic infections." (PMID 40980600, 2025). "Abortive infection of CD4+ T cells in lymphoid tissue further amplifies inflammatory death pathways, linking persistent innate sensing and IFN-I exposure to progressive immune depletion." (PMID 41488678, 2025). "Our findings underscore the therapeutic potential of targeting ARG2, as evidenced by the restorative effects of ARG2 blockade and knockdown on CD4+ T cell counts and the subsequent enhancement of the host's defense against secondary infections." (PMID 40860137, 2025). "Based on the critical role of CD4+ T cells in preventing S. aureus outgrowth in vivo, we next focused on how T cells shape innate immune cell responses during craniotomy infection." (PMID 39989461, 2025). "This restorative effect became even more evident by day 6 post-infection, with all baicalin doses significantly improving the CD4+/CD8+ ratio (P < 0.01 vs. virus-infected group)." (PMID 40406095, 2025). "While it is widely known that these CD4+ T cells play a critical role in infection and immunization, little is known about their role in cancer." (PMID 40641743, 2025). "The finding provides insights into the immune mechanisms and key regulators of HIV-1 maintenance in CD4+ T cells during the early stages of infection." (PMID 40838493, 2025). "Using a mouse model of S. aureus craniotomy infection, CD4+ T cells were critical for bacterial containment, as treatment of WT animals with anti-CD4 exacerbated infection that was similar to phenotypes in Rag1–/– mice." (PMID 39989461, 2025). "CD4+ T cells decreased throughout infection both in the periphery (P < 2 × 10–16) and in the superficial lymph nodes (SLNs) (P = 1.5 × 10–8)." (PMID 40662355, 2025). "During secondary infection, CD4+ T cell-dependent Th2-type memory is required for host protection against the parasite, which includes the induction and recruitment of alternatively activated macrophage (AAMacs) by IL-4/IL-13." (PMID 40501701, 2025). "IFNγ and TNF, which are produced by CD4+ effector T lymphocytes, are believed to be the main cytokines responsible for macrophage activation at the site of infection in TB." (PMID 40724823, 2025). "Contrasting with the stable Fluorospot data, S‐specific AIM+ CD4 T cells significantly declined post‐infection." (PMID 41427434, 2025). "Infection leads to depletion in CD4 + T-cells and the creation of large viral reservoirs within the body, resulting in an increased risk for infection." (PMID 39871382, 2025).
infection (continued). "Using the prescribed gating strategy, infection with WT L. major resulted in a significant expansion of DLD-specific CD4+ T cells in the spleens and dLNs at 5 weeks post-infection." (PMID 40096189, 2025). "The results ofquantitative real-time PCR (qRT-PCR) indicated that the transcription ofintegrin α4β7 in CD4+ T cells was upregulated from 15to 45 min post-infection, and reached a peak at 30 min, while the transcriptionof CCR9 remained unaffected." (PMID 40094365, 2025). "Secondly, to compare the Sm-specific T cell profile, and CD4 + T cell cytokine response to Schistosoma life-stage-specific antigens during repeat CHI to that in endemic-natural infection." (PMID 40707512, 2025). "In stark contrast, modern chimpanzee and gorilla CD4 orthologs are less supportive of entry by these viruses, consistent with natural selection having shaped CD4 to resist infection in these species." (PMID 40366257, 2025). "In contrast, more highly differentiated immune memory-associated IL-2-secreting T cells exhibited a delayed but sustained expansion, remaining elevated 28 days post-infection, which likely contributes to the formation of a durable pool of CD4+ memory T cells." (PMID 40472803, 2025). "It is well known that IFNγ, produced by TH1-polarized CD4+ T cells, plays a central role in controlling Plasmodium blood-stage infection." (PMID 40746561, 2025). "In summary, our study provides evidence that COVID-naïve, vaccinated individuals who later experience breakthrough infection display impaired Spike-specific CD4+ T-cell responses after the third vaccine dose, despite comparable antibody levels." (PMID 40977733, 2025). "Fate mapping studies have demonstrated that single naïve CD4+ T cells can give rise to effector and memory Th1 and Tfh cell populations during infection." (PMID 40391228, 2025). "Recent studies have shown that PLHIV are vulnerable to higher rates of severe breakthrough infection with CD4 count <350 cells/mm." (PMID 41283262, 2025). "infection the hosts can stimulate a humoral response, yet cell-mediated immunity plays a major role, in which both CD4+ and CD8+ lymphocytes are involved." (PMID 40707472, 2025). "For T cell-mediated immunity, IL-12 and IFNγ are key to controlling Mab infection and disease, and animal models consistently show an important role for CD4+ T cells in the lungs." (PMID 40415550, 2025). "CD4+ T cells primed during infection produced IFN-γ when restimulated ex vivo with Hc-Eng2 protein but not with peptides." (PMID 41061037, 2025). "During the initial infection of activated CD4+ T cells, TIM-TAM adopts an open conformation that exposes an internal ribosome entry site (IRES), allowing for cap-independent Tat synthesis and bypassing mTOR-mediated translational checkpoints." (PMID 40650088, 2025). "We found that the number of CD4+Treg cells increased with time after infection, while the number of CD8+Treg cells showed the opposite trend." (PMID 40416973, 2025). "To this end, we isolated CD4 T cells from mice that had undergone and cleared infection with LCMV WE, influenza A, or L. pneumophila or were chronically infected with LCMV Cl13." (PMID 40923840, 2025). "After infection, a significant increase in the number of circulating and infiltrating activated T CD4+ and CD8+ cells (CD69+/HLA-DR+ markers) is observed." (PMID 41472211, 2025). "On day 10 post infection (p.i.), the now differentiated progeny of the transferred T-bet ZsGreen Smarta CD4+ T cells were re-isolated." (PMID 41488650, 2025). "Infected monocytes have the potential to transfer virions to CD4 + T cells through a process known as trans-infection." (PMID 41366989, 2025). "Productive infection of activated primary CD4+ T cells with X4-tropic HIV-1NL4-3 was confirmed using p24 enzyme-linked immunosorbent assay (ELISA)." (PMID 41085277, 2025). "The frequency of TIGIT-expressing cells among splenic CD4+ T cells increased from weeks 2–4 post infection." (PMID 40526725, 2025).
infection (continued). "This demonstrated ability to separate patient samples collected pre- versus post-transplantation for CD4 T cells, and discrimination by development of infection after transplantation and receipt of ATG induction therapy." (PMID 40475763, 2025). "The clinical consequences are evident, since we and others have shown that low CD4+ and CD8+ T-cell counts are associated to a higher risk of infection after KT." (PMID 41312220, 2025). "With prolonged infection, the proportions of CD4+ Temra cells were elevated in both INRs and IRs compared to HCs." (PMID 40061947, 2025). "During the pathological process associated with SS, ectopic lymphocyte infiltration (mostly infiltration of CD4+ T cells) occurs; this is the first immune defense against injury or infection." (PMID 40426896, 2025). "Within the first 6−8 weeks of infection, a significant decrease in CD4+ T cells, a concomitant increase in viral load, and a corresponding increase in immune activation is observed." (PMID 40875618, 2025). "The GI tract is also one of the most damaged by the initial infection, indicated by a greater reduction in CD4+ T cells than in other tissues." (PMID 41480620, 2025). "We also observed a complete failure of BM progenitor cell populations to respond to infection together with elevated CD4+ T cell IFNγ production." (PMID 41296814, 2025). "IFN-γ critically helps in the contraction and phenotype of Ag-specific CD4+T cells generated during infections." (PMID 41009359, 2025). "Whereas the enhancement in CD8+ T cell function by activated CD4+ T cells is relatively well understood, the role of antitumor antibodies is unclear, in contrast to their known role in infection." (PMID 41002395, 2025). "The dysfunctional state of CD8+ T cells, termed exhaustion, is common in chronic infections and cancer and is exacerbated if CD4+ T cells are depleted prior to infection, but can be alleviated by replenishing with fresh CD4+ T cells." (PMID 40777021, 2025). "The general view of the origins of latently infected resting memory CD4+ T cells is that they arise from infection of CD4+ T cells activated during an immune response as the activated T cells return to an immunologically resting state." (PMID 40149913, 2025). "Cell-mediated immunity, primarily orchestrated by CD4+ T cells and macrophages, controls parasite levels but cannot fully clear the infection." (PMID 40590226, 2025). "Prior observations support the notion that CD4+ T cells expressing Mtb peptide:MHCII-specific TCRs must directly engage infected cells displaying these complexes to control infection." (PMID 40489538, 2025). "HLA-II-restricted CD4 + T cell immunity to HCMV is crucial for the control of the lifelong infection by this virus." (PMID 40608405, 2025). "For example, HIV-1 isolates derived from acute/early infection showed greater variations in replicative fitness and CD4/CCR5 affinity than HIV-1 obtained at different times during chronic infection (in the absence of treatment)." (PMID 40408432, 2025). "As a result, the CD4/CD8 ratio was significantly elevated in coinfected mice relative to single-infection and control groups (p < 0.05)." (PMID 41226526, 2025). "After prolonged infection, the GI tract maintains the lowest level of CD4+ T cells, which is accompanied by alterations to the composition of the gastrointestinal microbiome." (PMID 41480620, 2025). "Before injections of TCID5O for SIVmac239 infection, the average scores of CD4 T-cell count, CD8 T-cell count, and CD4/CD8 ratio were 1120.79 ± 514.25, 605.81 ± 201.47, and 1.96 ± 0.78, respectively." (PMID 40093003, 2025). "Despite these advances, approximately half of newly diagnosed PLWH present in later stages of infection, ie, with CD4+ T-cell counts below 350/μL, with repercussions on immune reconstitution and clinical outcome." (PMID 41267933, 2025).
infection (continued). "The indispensable roles for innate cytokines during primary infection are well appreciated, but, more importantly, early IL-6 is paramount for the expansion of primed CD4+ T cells and enhances the production of IL-2, TNF, and IFN-γ during secondary infections." (PMID 40279312, 2025). "Most children produced robust CD4+ T cell responses during infection and developed memory CD4+ T cells; however, young children less than 4 years old often had undetectable CD4+ T cell responses compared with older children and adults." (PMID 40906527, 2025). "Tem cells (CD44+ CD62L−, gated on CD4+ FOXP3+) were increased by MNV infection in Ncf190H mice, whereas naive Tregs (CD44− CD62L+, gated on CD4+ FOXP3+) and Tcm/ Tvm cells (CD62L+ CD44+, gated on CD4+ FOXP3+) were decreased." (PMID 39939342, 2025). "A continuous attack of the immune system causes a significant fall in the number CD4 T-cells below 1000 cells/μl and a further decline of CD4/CD8 ratio below ~1 within the first 14 days of infection." (PMID 40093003, 2025). "Although HIV treatment has advanced, the infection can still progress to a state of immunosuppression characterized by a marked reduction in CD4 T lymphocytes (CD4 T)." (PMID 40559606, 2025). "An obstacle to the evaluation of neutralization activity remains the lack of standardizable, high-throughput assays to study HIV-1 inhibition in an environment similar to in vivo infection of primary CD4 T cells with replicating virus." (PMID 39836706, 2025). "Of the 2689 eligible cases, 1073 were classified as long-term infection based on CD4+ T lymphocyte count and disease status at diagnosis, and 1625 (60.2%) underwent LAg avidity enzyme immunoassay." (PMID 40128682, 2025). "MDMs underwent a high degree of IFN-γ receptor signaling regardless of their ability to present MHCII-bound Mtb peptides to cognate CD4+ T cells but required cognate interactions to fully upregulate glycolytic gene expression and control infection." (PMID 40489538, 2025). "Lymphoid tissues are the primary locations of HIV-1 replication during untreated infection and contain the majority of infected CD4+ T cells in the body after ART40." (PMID 41279654, 2025). "All infected mice (except one in HIV-B), exhibited CD4+ T cells depletion post infection with variable nadir levels and duration compared to the controls." (PMID 40308596, 2025). "Using the collected data on antibody and cell responses, we assessed the proportions of responders and non-responders (S-specific IgG titres and fold activation of CD4 T-cells) in all groups after vaccination, infection, and hybrid-induced immunity." (PMID 41280926, 2025). "Infection of CD6-deficient mice with a neurotropic murine coronavirus resulted in greater activation and expansion of CD4 T cells in the draining lymph nodes." (PMID 39679790, 2025). "Lower levels of CD4 EM TIGIT+ T cells were also predictive of freedom from infection with and HR of 2.5 (95% CI 1.3-4.9)." (PMID 40475763, 2025). "Overall, revaccination significantly enhances T-cell responses following infection, particularly within the mucosal compartments, leading to increased numbers of both CD4 and CD8 T cells at the sites of viral replication." (PMID 40552302, 2025). "At the molecular level, the comorbid state is characterized by persistent CD4+ T cell activation and heightened neutrophilic inflammation, forming a vicious cycle of “infection–inflammation–tissue destruction." (PMID 41227036, 2025). "As CD4+ T cells are usually recovered in low cell numbers during these infections, we decided to assess their phenotype in the spleen at an early time point." (PMID 41488650, 2025). "Intravenous CD45 antibody labeling was performed on α-CD4- or isotype control antibody-treated mice at 3 weeks post-infection to test this possibility." (PMID 40489538, 2025).